TALDO1 (transaldolase 1)
Diseases named in the same sentence as TALDO1 in open-access papers (continued):
Sharing a sentence is not in itself a finding about the gene and the disease.
pulmonary arterial hypertension (1 paper, 2024). Pulmonary arterial hypertension (PAH) is a group of diseases characterized by mean pulmonary artery pressure >20 mmHg and elevated pulmonary arterial resistance leading to right heart failure. "The glycolysis genes (ACSS2, ALAS2, ALDH3A1, ADOC3, NT5E, and TALDO1) identified in this study play important roles in the development of pulmonary arterial hypertension, providing new evidence for the involvement of glycolysis in PAH." (PMID 38837574, 2024).
pulmonary fibrosis (1 paper, 2025). Chronic progressive interstitial lung disorder characterized by the replacement of the lung tissue by connective tissue, leading to progressive dyspnea, respiratory failure, or right heart failure. "TALDO1 is activated by nuclear factor erythroid-2-related factor 2 (NRF2), a promoter of tumor progression, which inhibits EMT by suppressing snail expression during pulmonary fibrosis in mice experiments." (PMID 39997396, 2025).
squamous cell carcinoma of the (1 paper, 2022). "In addition, genetic polymorphisms in TALDO1 were closely correlated with squamous cell carcinoma of the head and neck." (PMID 35078458, 2022).
Stroke (1 paper, 2025). Sudden impairment of blood flow to a part of the brain due to occlusion or rupture of an artery to the brain. "We identified 4 proteins linked to glucose metabolism that were significantly altered post-stroke: L-lactate dehydrogenase A chain (Ldha), 6-phosphogluconolactonase (Pgls), glycogenin-1 (Gyg1), and transaldolase (Taldo1)." (PMID 41342963, 2025).
viral infection (1 paper, 2018). "Analysis using IPA software suggested that eight of the targeted proteins (ATP5B, GPT2, HSPA9, MAPK1, PDIA3, PDIA6, PSMC5, and TALDO1) were involved in virus infection and their lower protein abundance may inhibit viral infection." (PMID 29404200, 2018). "Eight proteins (GPT2, HSPA9, MAPK1, PDIA3, PDIA6, PSMC5, TALDO1, and ATP5B) were predicted/known to be involved in viral infection." (PMID 29404200, 2018). "The change in abundance of eight of the targeted proteins (GPT2, HSPA9, MAPK1, PDIA3, PDIA6, PSMC5, TALDO1, and ATP5B) was predicted to collectively inhibit viral infection (pathway analysis)." (PMID 29404200, 2018).
cancer (18 papers, 2012 to 2025). A tumor composed of atypical neoplastic, often pleomorphic cells that invade other tissues. "TALDO1 may also play a role in cancer drug resistance; higher levels of TALDO1 expression were associated with poor response to BC HER2 inhibitors in BC patients." (PMID 33499132, 2021). "Exosomes from both the cell lines contained G6PD, transketolase and transaldolase 1 which are part of the pentose phosphate pathway and may be diagnostic of late stage cancer." (PMID 29262670, 2017). "The results showed that glycolysis‐related genes, such as Nasp, Got1 and Taldo1, were highly expressed in the cancer cells of KAR mice." (PMID 40621620, 2025). "TALDO1 is an enzyme that is involved in the pentose phosphate pathway, which is a key player in cellular metabolism and proliferation processes in cancer cells." (PMID 34282517, 2021). "The G6PD, PGD, TKT, and TALDO1 support glucose flux and generate purines, which are building blocks of DNA and RNA, which help to accelerate proliferation in cancer cells." (PMID 33922165, 2021). "Our findings suggest that MS17 upregulated HSPPA9, LCP1 and MSN and downregulated TALDO1 in SW620 cells, which could affect the JAK-STAT signaling pathway and associated with apoptosis, proliferation, and immune response, resulting in anti-cancer effects." (PMID 38542474, 2024). "As an example, consistent with studies in cancer cells, we found that Nrf2 significantly boosted several genes in the pentose phosphate pathway, including those for glucose-6-phosphate dehydrogenase (G6pd), transaldolase 1 (Taldo1), and phosphogluconate dehydrogenase (Pgd)." (PMID 33491671, 2021). "In our present study, we found that some enzymes identified from MV fractions were already proposed to play a role in cancer therapy as therapeutic targets (OAT, TALDO1) and resistance against chemotherapy agents (BLMH)." (PMID 33499132, 2021). "MS17 induced the upregulation of PRDX2 and TKT with the TALDO1 downregulation in SW620 cells, which may interfere with the cancer metabolism and increase ROS production to induce cellular stresses, leading to apoptosis." (PMID 38542474, 2024). "Several enzymes in the oxidative (e.g., G6PD) as well as non-oxidative (e.g., TALDO1, TKT) phases of pentose phosphate pathway was highly expressed in pRCC type 1, associated with increased demand for ribonucleotides in the rapidly proliferating cancer cells." (PMID 38703764, 2024). "NRF2 plays a crucial role in promoting the proliferation of cancer cells and metabolism process in lung cancer cells, including the direct transcriptional regulation of PPP-related enzymes such as G6PD, PGD, TKT, and TALDO1, which are responsible for NADPH regeneration." (PMID 33922165, 2021).
tumor (16 papers, 2012 to 2025). "Our findings revealed that the mRNA levels of Pfn2, Taldo1, and Ftcd were significantly downregulated in tumor tissues of Hepa1‐6 implantation models." (PMID 40018995, 2025). "In another study, the examination of the proteomic profile of serum extracellular vesicles from subjects with BC showed that TALDO1 a rate-limiting enzyme of the pentose phosphate pathway was found to be a biomarker of tumor metastasis." (PMID 39195217, 2024). "We also observed that the 4 prognosis-associated genes RHOB, TALDO1, HLA-DPA1, and TKT were simultaneously elevated in the tumor and peripheral blood in patients with HCC." (PMID 35856557, 2022). "To investigate the prognostic ability of SLC1A5/TALDO1 co-expression independently of tumor size, grade and nodal stage, we performed multivariate Cox regression." (PMID 34282517, 2021). "Furthermore, 4 common prognosis-associated genes (RHOB, TALDO1, HLA-DPA1, and TKT) were significantly overexpressed in the paired tumor tissue and blood." (PMID 35856557, 2022). "Notably, we observed that the expression of these genes was significantly elevated in tumor tissues when compared to adjacent non-tumor tissues (p < 0.001), with TALDO1 exhibiting the highest level of expression." (PMID 37351550, 2023).
TALDO1 also shares sentences with these, for which no sentence is quoted: Cirrhosis (6 papers); anemia (2); gastric cancer (2); infection (2); liver cancer (2); upper tract urothelial carcinoma (2); acute liver failure (1); amyotrophic lateral sclerosis (1); cholestasis (1); colorectal cancer (1); congenital heart disease (1); Creutzfeldt-Jakob disease (1); cystinuria (1); Dent disease (1); distal renal tubular acidosis (1); Failure to thrive (1); fibrosis (1); gastric adenocarcinoma (1); head and neck carcinoma (1); Hepatosplenomegaly (1); hydrops fetalis (1); Hypercalciuria (1); Hypoalbuminemia (1); liver dysfunction (1); male infertility (1); medulloblastoma (1); metabolic disease (1); migraine (1); multiple sclerosis (1); ovarian carcinoma (1).
A further 8 diseases each share a sentence with TALDO1 in 1 paper.